LIF (LIF interleukin 6 family cytokine)
Diseases named in the same sentence as LIF in open-access papers (continued):
Sharing a sentence is not in itself a finding about the gene and the disease.
breast carcinoma (71 papers, 2007 to 2026). "In breast cancer, overexpression of LIF, predominantly from cancer-associated fibroblasts, is observed." (PMID 40977686, 2025). "In a mouse model of breast cancer, LIF was shown to operate through M2 like- tumor associated macrophages to silence CD8+ T cells via epigenetic modification." (PMID 37033980, 2023). "Compared with normal breast tissue, significantly elevated mRNA levels of CXCR2 and LIF in breast cancer-associated adipocytes, and the expression of CXCL1-3, and CXCL8 in breast cancer tissue were up-regulated." (PMID 35280694, 2022). "This study also reveals an important mechanism underlying metabolic reprogramming of breast cancers, and identifies LIF and its downstream signaling as potential therapeutic targets for breast cancers, especially those with LIF overexpression." (PMID 35440095, 2022). "Based on the results, cancer-associated fibroblasts are producers of LIF in the cocultivation system with breast cancer cells." (PMID 34947829, 2021). "The amount of LIF secreted by a tumor seems to regulate cancerogenesis; LIF overexpression in breast cancer patients is significantly associated with an unfavorable rate of survival without relapses." (PMID 30899759, 2019). "LIF is frequently overexpressed in many solid tumors, including breast cancer, colorectal cancers and nasopharyngeal cancers, and the overexpression of LIF in tumors is often associated with poor prognosis of patients." (PMID 25726527, 2015). "Among the cytokines and chemokines, we found that TGFα significantly modulated LIF that has been demonstrated to be associated to breast cancer transformation and progression." (PMID 25344915, 2014). "Notably, overexpression of LIF is significantly associated with a worse relapse-free survival rate in breast cancer patients and the amount of LIF secreted appears to regulate tumorigenesis." (PMID 26329521, 2015). "Furthermore, overexpression of LIF is significantly associated with a poorer relapse free survival in breast cancer patients." (PMID 24553191, 2014). "Our results show that higher LIF expression is associated with poorer relapse free survival of breast cancer patients, indicating that LIF could be an important prognostic marker for breast cancer patients." (PMID 24553191, 2014). "LIF has been reported to drive metabolic reprogramming in cancer cells, particularly by promoting glycolysis and thereby fostering tumorigenesis in breast cancer." (PMID 39857986, 2025). "Overexpression of LIF has been shown to initiate autocrine signaling, thereby driving the progression of breast cancer cells." (PMID 40075639, 2025). "LIF expression is known to be upregulated via epigenetic changes and upregulation of LIF is essential for the development of breast cancer via autocrine mechanisms." (PMID 38347540, 2024). "Previous research has shown that LIF is highly expressed in various tumor tissues (e.g. pancreatic cancer, breast cancer, prostate cancer, and colorectal cancer) and promotes cancer cell proliferation, migration, invasion, and differentiation." (PMID 39169307, 2024). "Previous studies have shown that the expression of LIF is increased in various tumor types, including breast cancer, pancreatic cancer, nasopharyngeal cancer, and prostate cancer." (PMID 39169307, 2024). "LIF was shown to promote migration and metastasis in breast cancer through the AKT-mTOR pathway, and elevation of VEGF-A in breast cancer is typically associated with poor prognosis and higher rates of metastasis." (PMID 38397942, 2024). "CXCL1 also acts on cancer-associated adipocytes, causing STAT3 activation in them, which leads to the production of LIF which in turn increases CXCL1 production in breast cancer cells." (PMID 37108425, 2023).
breast carcinoma (continued). "For instance, LIF is frequently overexpressed in many solid tumors including colorectal cancers, breast cancers, and skin cancers, and LIF overexpression in tumors correlates with poor prognosis of patients." (PMID 37134077, 2023). "Inhibitory cytokines, in particular, leukemia inhibitory factor (LIF), are known breast cancer metastasis suppressors." (PMID 36902406, 2023). "Our results indicate that CAAs can regulate the migration and invasion of breast cancer cells via the LIF/Stat3 axis." (PMID 35280694, 2022). "Our recent studies have shown that LIF is frequently overexpressed in breast cancers (~50-60%) across different genetic subtypes, and is associated with poor prognosis in breast cancer patients." (PMID 35440095, 2022). "Together, these data suggest that LIF promotes glucose uptake and drives glycolysis in breast cancer cells." (PMID 35440095, 2022). "In the RNA-Seq data of the previous study, we found that the cytokine LIF was differentially expressed between adipocytes and CAAs 11, which implied that LIF has a potential impact on the microenvironment of breast cancer." (PMID 35280694, 2022). "LIF was highly expressed in adipocytes adjacent to breast cancer of clinical breast cancer specimens, which was correlated with Stat3 phosphorylation in breast cancer." (PMID 35280694, 2022). "One study of breast cancer saw that LIF was able to significantly increase proliferation of estrogen receptor-positive cell lines, whereas estrogen receptor-negative cell lines did not have their proliferation impacted by LIF." (PMID 35204717, 2022). "We further used the results from a group of breast cancer patients who received 18F-fluorodeoxyglucose (18F-FDG) microPET scans to evaluate the impact of LIF overexpression on glucose uptake in breast tumors of breast cancer patients in vivo." (PMID 35440095, 2022). "The effect of LIF on Glut1 PM translocation was further examined in breast cancer cells transfected with vectors expressing Myc-Glut1." (PMID 35440095, 2022). "This desmonstrates that breast cancer cells induce CAAs to highly express LIF and secrete LIF protein." (PMID 35280694, 2022). "LIF is frequently overexpressed in many cancer types, including breast cancer, which promotes proliferation, metastasis and therapeutic resistance of cancer cells." (PMID 35440095, 2022). "In summary, this study demonstrates an important role of LIF overexpression in glucose metabolism reprogramming in breast cancers, which contributes to breast tumorigenesis." (PMID 35440095, 2022). "Here we report that CAAs and breast cancer cells communicate with each other by secreting the cytokines leukemia inhibitory factor (LIF) and C-X-C subfamily chemokines (CXCLs), respectively." (PMID 35280694, 2022). "This study demonstrates that elevated LIF expression in breast cancer cells promoted glycolysis with significantly increased glucose uptake, lactate production, and glycolytic rate." (PMID 35440095, 2022). "Currently, the precise role and mechanism of LIF in breast cancer is poorly understood, and the role of LIF in metabolic rewiring in breast cancer is still unclear." (PMID 35440095, 2022). "LIF, a multifunctional cytokine, is frequently overexpressed in many types of solid tumors, including breast cancer, and plays an important role in promoting tumorigenesis." (PMID 35440095, 2022). "Next, IHC was used to evaluate the correlation between the expression of LIF in adipocytes adjacent to breast cancer and Stat3 phosphorylation in breast cancer tissues." (PMID 35280694, 2022). "Specific inhibition of LIF/LIFR interactions has been proposed as a promising target for breast cancer therapy." (PMID 35163731, 2022). "In breast cancer, the most studied members of this family are interleukin-6 (IL-6), leukemia inhibitory factor (LIF), oncostatin M (OSM), and interleukin-11 (IL-11)." (PMID 35163731, 2022).
breast carcinoma (continued). "Breast cancer can have conflicting effects of LIF, with both pro- and anti-tumor effects able to be seen." (PMID 35204717, 2022). "LIF overexpression in the breast cancer cells activated the AKT signaling to promote Glut1 PM translocation, which in turn led to enhanced glucose uptake and glycolysis." (PMID 35440095, 2022). "In this study, we found that LIF is a novel and unique driver for glucose metabolic reprogramming in breast cancer." (PMID 35440095, 2022). "Together, these results demonstrate that LIF promotes glucose uptake and glycolysis in breast cancer cells to promote cell proliferation and tumor growth." (PMID 35440095, 2022). "Within some breast cancer cell lines, DNA hypomethylation results in increased transcription of the LIF gene, and this epigenetic upregulation contributes to cancer progression." (PMID 35204717, 2022). "Next, RNA-seq was used to screen secreted proteins of breast cancer cells that induce CAAs to express LIF." (PMID 35280694, 2022). "In clinic, LIF overexpression often correlates with poor prognosis in many cancer types, including breast cancer." (PMID 35440095, 2022). "We found that the expression of LIF and its receptor increased in co-cultured adipocytes and breast cancer cells, respectively." (PMID 35280694, 2022). "Results from our previous study showed that MCF7 and MDA-MB 231 cells have relatively high endogenous LIF expression compared with other breast cancer cells." (PMID 35440095, 2022). "LIF is a pro-inflammatory cytokine secreted by CAAs, which promotes migration and invasion of breast cancer cells via the Stat3 signaling pathway." (PMID 35280694, 2022). "In clinical breast cancer pathology samples, the up-regulation of LIF in paracancerous adipose tissue was positively correlated with the activation of Stat3 in breast cancer." (PMID 35280694, 2022). "Human recombinant LIF (rhLIF) protein was used to evaluate the effect of LIF on breast cancer cells in vitro." (PMID 35280694, 2022). "It has been demonstrated that LIF promotes breast cancer cell proliferation in culture and in vivo, as well as EMT in MCF-7 and T47D tumor cells, and knockdown of endogenous LIF have reversed EMT in MDA-MB231 cells." (PMID 35163731, 2022). "While these studies began to unravel a critical role of LIF in cancer, the molecular underpinnings of this cytokine in cancer, especially in breast cancer, are still far from clear." (PMID 35440095, 2022). "Recent studies, including ours, have shown that LIF promotes the tumorigenesis of many types of solid tumors, including breast cancer." (PMID 35440095, 2022). "Ectopic LIF expression significantly increased glucose uptake in all of these breast cancer cells tested." (PMID 35440095, 2022). "Results from this study suggest that glucose metabolic reprogramming driven by LIF is critical for breast tumorigenesis, which is therapeutically targetable for LIF-overexpressing breast cancer." (PMID 35440095, 2022). "The increased lactate production by LIF can be largely abolished by treating breast cancer cells with LIF neutralization antibody (LIF neu-ab)." (PMID 35440095, 2022). "Studies of breast cancer cell lines have shown that cancer cells internalize LIF, which stimulates growth and colony formation of cancer cells, but LIF has little effect on normal breast epithelial cells." (PMID 35204717, 2022). "Many studies have proved that LIF plays an important role in breast cancer, pancreatic cancer, gastric cancer, and ovarian cancer." (PMID 35992780, 2022). "Results from this study further show that AKT activation by LIF is an important mechanism by which LIF rewires glucose metabolism in breast cancer cells." (PMID 35440095, 2022). "While LIFR expression is similar between different breast cancer cell lines, LIF expression is highly varied and correlates with the metastatic potential of the cell lines." (PMID 35204717, 2022).
breast carcinoma (continued). "In this study, we observed that both LIF overexpressed in breast cancer cells and recombinant LIF protein added into the culture medium rewired glucose metabolism in breast cancer cells." (PMID 35440095, 2022). "We found that the pro-inflammatory cytokine LIF is a new mediator involved in the CAA-induced breast cancer invasion and metastasis." (PMID 35280694, 2022). "Our findings reveal that the interaction of adipocytes with breast cancer cells depends on a positive feedback loop between the cytokines LIF and CXCLs, which promotes breast cancer invasion and metastasis." (PMID 35280694, 2022). "LIF signaling within breast cancer is seen to limit the effectiveness of treatment with histone deacetylase inhibitors in cell lines and patient-derived xenograft or allograft models." (PMID 35204717, 2022). "But LIF does not seem to be solely dependent on STAT3 activation in order to be pro-oncogenic, and some have even pointed to tumor cell dormancy induction via a LIF : LIFR : STAT3 axis in breast cancer to bone marrow metastasis." (PMID 34395259, 2021). "Blockade of LIF signaling with the LIF receptor antagonist reverses these phenotypes and offers a possible therapeutic approach in breast cancer." (PMID 34947829, 2021). "Through activation of the AKT-mTOR signaling pathway, LIF induces breast cancer cell proliferation, invasion, and metastasis." (PMID 34947829, 2021). "The current study shed light on the interaction of breast cancer cells and CAFs and revealed that breast cancer cells stimulated CAFs to produce LIF." (PMID 34947829, 2021). "The continuous exposure of breast cancer cell populations to LIF resulted in an increase in the breast CSC marker relative to untreated cells in both populations." (PMID 34947829, 2021). "CAFs in contact with breast cancer cells secrete LIF upon stimulation by specific factors expressed by the breast cancer cells." (PMID 34947829, 2021). "To validate the impact of LIF on breast cancer stemness, we treated breast cancer cells with human LIF protein." (PMID 34947829, 2021). "Our in vitro study revealed that breast cancer cells stimulated CAFs to secrete LIF, which is in agreement with another study." (PMID 34947829, 2021). "In this study, a coculture system of CAF cells isolated from breast cancer patients with breast cancer cells was used to investigate LIF production from CAFs." (PMID 34947829, 2021). "As far as we investigated, this is the first attempt to study the regulatory influence of CAFs on breast cancer stemness through LIF function." (PMID 34947829, 2021). "We found that LIF was frequently overexpressed by CAFs and that LIF expression is necessary for dedifferentiation of breast cancer cell phenotype and regaining of cancer stem cell properties." (PMID 34947829, 2021). "Our findings indicated that LIF treatment transforms breast cancer cells into a stem-like state and acquires CSC properties." (PMID 34947829, 2021). "While LIFRβ expression seems to be negatively correlated with breast cancer growth and metastasis, high expression of LIF is positively correlated." (PMID 34395259, 2021). "Culturing breast cancer cells with LIF induced high levels of Nanog and Oct4 expression, demonstrating characteristics of cancer cell stemness." (PMID 34947829, 2021). "The capability of the LIF to induce cancer cell plasticity makes it a good choice for the treatment of breast cancer by neutralizing its function." (PMID 34947829, 2021). "Yue and colleagues reported that LIF provoked epithelial to mesenchymal transition (EMT) in breast cancer cell lines via the induction of miR-2129." (PMID 32651426, 2020). "Previous work has demonstrated that LIF can induce STAT3 signaling in breast cancer cells, and STAT3 has been previously identified as a pro-dormancy factor in ER+ breast cancer cells and prevents colonization of the bone by disseminated tumor cells." (PMID 32023849, 2020).
breast carcinoma (continued). "Further studies will be required to examine the mechanism of action for LIF effects on breast cancer cells in the context of the bone microenvironment." (PMID 32023849, 2020). "Dhingra and others showed that exogenous LIF stimulated the growth of ER-positive breast cancer cells in cultured cells through binding to LIFR12." (PMID 32651426, 2020). "Studies have shown that LIF overexpresses in many tumors including breast cancer and promotes growth and metastasis of tumors." (PMID 32264877, 2020). "It has been previously established that LIFR expression on breast cancer cells promotes tumor dormancy in the bone marrow and that several of the gp130 cytokines (LIF, OSM, and CNTF) are able to signal through LIFR." (PMID 32023849, 2020). "For example, leukemia inhibitory factor (LIF) secreted by osteoblasts and bone marrow stromal cells limit growth of breast cancer DTCs in bone by activating LIFR: STAT3 signaling." (PMID 31447846, 2019). "A LIF signal is also expressed at high levels in a wide spectrum of human cancers, including melanomas, skin, kidney, prostate, pancreas and breast cancer, where cell proliferation is stimulated by paracrine and autocrine pathways, as in embryo implantation." (PMID 30899759, 2019). "LIF is frequently overexpressed in different types of human tumors, including breast cancer, colorectal cancer, nasopharyngeal carcinoma, lung cancer and melanoma." (PMID 26716902, 2016). "Our recent report showed that LIF promotes the invasion and migration of in vitro cultured breast cancer cells and lung metastasis in nude mice injected with breast cancer cells via the tail vein." (PMID 26716902, 2016). "Since STAT3 can be activated by a variety of cytokines, including IL-11, CNTF, LIF and G-CSF, in breast cancer, it is crucial to identify those tumors that depend on IL-6." (PMID 27602583, 2016). "LIF overexpression is frequently observed in many human tumors, including breast cancer, colorectal cancer, lung cancer, head and neck cancer, melanoma and nasopharyngeal carcinoma." (PMID 26716902, 2016). "Overexpression of LIF in breast cancer and colorectal cancer cells promotes cancer cells to acquire mesenchymal features, increase the expression of mesenchymal markers, including Vimentin and N-cadherin, and decrease the expression of E-cadherin." (PMID 26716902, 2016). "LIF has been reported to promote the progression of malignancies of many solid tumors, including rhabdomyosarcoma, choriocarcinoma, melanoma, breast cancer and colorectal cancer." (PMID 25726527, 2015). "Taken together, these data indicate that LIF-activated fibroblasts induce onset of a proinvasive tumour microenvironment in vivo, in a syngenic and orthotopic mice model of breast cancer." (PMID 26667266, 2015). "GRN enhanced STAT3 DNA binding and also increased the time-integrated amount of LIF-induced STAT3 activation in breast cancer cells." (PMID 26000098, 2015). "For example, results from our recent study showed that overexpression of LIF promotes growth and metastasis of breast cancer cells both in vitro and in vivo through the activation of the AKT-mTOR pathway." (PMID 25726527, 2015). "LIF is frequently overexpressed in a variety of solid tumors including colorectal cancers, breast cancers and skin cancers." (PMID 25726527, 2015). "LIF promotes cell proliferation and anchorage-independent growth of breast cancer cells in vitro, and the growth of xenograft breast tumors in vivo." (PMID 24553191, 2014). "LIF also promotes invasion and migration of breast cancer cells in vitro and metastasis of breast cancer cells in vivo." (PMID 24553191, 2014). "Both exogenous LIF and LIF expressed in cells show promoting effects on tumorigenesis and metastasis of breast cancer, suggesting that LIF functions in both autocrine and paracrine manners." (PMID 24553191, 2014).